RACK1 (receptor for activated C kinase 1)
Diseases named in the same sentence as RACK1 in open-access papers (continued):
Sharing a sentence is not in itself a finding about the gene and the disease.
breast cancer (continued). "Next, we determined whether RACK1 silencing affects β-catenin mRNA expression in two breast cancer cell lines." (PMID 37848434, 2023). "In summary, we uncovered the interaction between CCDC102B and RACK1, which could be one of the mechanisms involved in the early-stage metastasis of breast cancer." (PMID 35957886, 2022). "The aggressive behavior of CCDC102B in breast cancer cells could be reversed by the expression of RACK1." (PMID 35957886, 2022). "Considering that RACK1 decreased the stability of CCDC102B, we hypothesized that RACK1 might exert its effects on breast cancer cell metastasis by regulating the degradation of CCDC102B." (PMID 35957886, 2022). "In people with breast cancer, RACK1 is also a significant prognostic marker for survival." (PMID 33777753, 2021). "Given the potential role of OXER1 and RACK1 in BC progression, we evaluated the possibility that expression of the two corresponding mRNAs represent a useful predictive marker of survival for specific subtypes of mammary tumors." (PMID 33311444, 2020). "Interestingly, Rack1 also interacts with Rho and activates RhoA/Rho kinase pathway to enhance breast cancer metastasis." (PMID 31113450, 2019). "In particular, higher Rack1 level is an independent predictor for poor prognosis in breast cancer." (PMID 31113450, 2019). "To determine whether Rack1 is necessary for Anxa2 tyrosine phosphorylation, we silenced the expression of Rack1 in two drug-resistant breast cancer cell lines using two different Rack1-specific siRNAs." (PMID 31113450, 2019). "To determine whether Rack1 contributes to drug susceptibility, we used small interfering RNAs (siRNAs) to downregulate the expression of Rack1 in MDR breast cancer cells." (PMID 31113938, 2019). "However, very few reports exist so far showing abnormal RACK1 expression at the protein level in glioma, with immunohistochemical data only available for breast cancer, gastric cancer, and esophageal squamous cell carcinoma." (PMID 27763568, 2016). "Altogether, our data support a tumor promoter role of Rack1 in breast cancer." (PMID 27754360, 2016). "This is similar to some previous studies on the roles of RACK1 in breast cancer and thyroid cancer." (PMID 27170279, 2016). "In contrast, some reports suggest that RACK1 expression is reduced in breast cancer." (PMID 21978545, 2011). "Several studies have shown that RACK1 promotes tumor progression and malignancy in colorectal, esophageal, and squamous cell carcinomas of the mouth and lungs, as well as increases the proliferation, migration, and metastasis of breast cancer and is considered an independent prognostic factor." (PMID 40060229, 2025). "Moreover, RACK1 silencing induced an apparent increase in the G2/M phase ratio, similar to previous reports that RACK1 knockdown led to an increase in the G2/M phase ratio, despite the fact that RACK1 inhibited proliferation in their cell model (non-breast cancer)." (PMID 37848434, 2023). "However, whether ribosomal RACK1 regulates the stability of β-catenin in breast cancer needs to be further investigated in the future." (PMID 37848434, 2023). "In addition, RACK1 was positively correlated with Ki67 expression in breast cancer tissues." (PMID 37848434, 2023). "Thus, RACK1 is essential for the proliferation of breast cancer cells in vitro." (PMID 37848434, 2023). "Furthermore, we investigated the role of RACK1 in breast cancer cell migration and metastasis." (PMID 35957886, 2022). "Thus, the interaction between CCDC102B and RACK1 regulates the metastatic ability of breast cancer." (PMID 35957886, 2022). "A breast cancer study using IHC of 160 primary breast carcinomas revealed that higher RACK1 expression was correlated with shorter overall survival, and suggested a correlation between RACK1 and the commonly used clinicopathological biomarkers (e.g., Ki-67 and ER) in breast cancer." (PMID 33462336, 2021). "We supposed that Rack1 knockdown may attenuate P-gp activity in breast cancer cells." (PMID 31113938, 2019).
breast cancer (continued). "Thus, our results support the tumor-promoter role of Rack1 in breast cancer." (PMID 31113450, 2019). "Recently, studies indicated that RACK1 plays a dramatic role in the occurrence, development, and metastasis of various cancers, including non-small-cell lung cancer, hepatocellular carcinoma, esophageal squamous cell carcinoma, breast cancer, and prostate cancer." (PMID 30962803, 2019). "Indeed, it has been reported that RACK1 may play a role in the promotion of breast cancer cell migration, by binding to and activating RHOA." (PMID 28686225, 2017). "Thus, we supposed that Rack1 functions as a positive regulator in breast cancer." (PMID 27754360, 2016). "Thus, our study supports the tumor promoter role of Rack1 in breast cancer." (PMID 27754360, 2016). "Besides, RACK1 may promote the ability of proliferation and the tendency of invasion and metastasis of breast cancer, and the decrease of ubiquitin degradation of RACK1 in ovarian cancer leads to the enhancement of the proliferation, migration, and invasion of ovarian cancer cells." (PMID 38398158, 2024). "Since function of RACK1 is diverse and extensive in breast cancer, they mentioned that the investigation of the roles of USP41-mediated RACK1 in cancer cell migration are necessary." (PMID 36675208, 2023). "We then analyzed the endogenous interaction of these proteins in breast cancer cells using Co-IP assays with anti-PSMD2, RACK1, and β-catenin antibodies." (PMID 37848434, 2023). "We uncovered that RACK1 promotes the stability of β-catenin, thereby facilitating the activation of the canonical WNT pathway in breast cancer cells." (PMID 37848434, 2023). "In one study, it was shown that LTV1 was substoichiometric in breast cancer cells, producing reduced RPS10 and RACK1 ribosomes." (PMID 34923969, 2021). "Rack1 is required for the invasive and metastatic potential of MDR breast cancer cells through mediating the binding of Anxa2 to Src, thereby facilitating Anxa2 phosphorylation by Src kinase." (PMID 31113450, 2019). "We showed that Rack1 and Anxa2 are required for the invasive and metastatic potential of multidrug-resistant (MDR) breast cancer cells." (PMID 31113450, 2019). "Silencing of Rack1 expression significantly inhibited the proliferation and invasion of MDR breast cancer cells." (PMID 27754360, 2016). "Knockdown of Rack1 significantly inhibited the proliferation and invasion of MDR breast cancer cells." (PMID 27754360, 2016). "In addition, RACK1 may protect cells from apoptosis in breast cancer." (PMID 21978545, 2011). "In breast cancer cells, RACK1 binds to PSMD2 within the proteasome and this binding prevents proteasome-mediated degradation of ubiquitinated β-catenin, resulting in the activation of the Wnt signaling pathway and promotion of breast cancer proliferation." (PMID 40940922, 2025). "In addition, we treated RACK1-silenced cells with MG132 and found that the binding ability of PSMD2 to poly-ubiquitinated β-catenin was significantly enhanced in both breast cancer cells." (PMID 37848434, 2023). "Furthermore, according to the breast cancer data in TCPA, the RACK1 co-expression gene set was also enriched in the proteasome pathway." (PMID 37848434, 2023). "Knockdown of PSMD2 did not affect the protein levels of β-catenin and RACK1 in two breast cancer cells." (PMID 37848434, 2023). "Thus, all of these reports indicate the relationship among RACK1, CCDC102B and the NF-κB pathway, which has important functions in breast cancer metastasis." (PMID 35957886, 2022). "LncRNA PCAT-1, elevated in breast cancer patients, directly interacts with the activated protein C kinase-1 (RACK1) protein to prevent RACK1 binding to HIF-1α, thereby protecting HIF-1α from RACK1-induced oxygen-dependent degradation of lncRNA." (PMID 36226050, 2022).
breast cancer (continued). "Mechanistically, receptor for activated C kinase 1 (RACK1), which was negatively correlated with breast cancer prognosis, bound to the third coiled-coil structure of CCDC102B, which includes two putative KFERQ-like motifs, and participated in the lysosomal degradation of CCDC102B through CMA." (PMID 35957886, 2022). "The accurate function of Rack1 in promoting the aggressive behavior in drug-resistant breast cancer cells has not been thoroughly determined." (PMID 31113450, 2019). "In the breast cancer cell lines, non-canonical autophagy induction and Bcl-xL increment were also detected when RACK1 siRNA was treated." (PMID 28518135, 2017). "Previously, p-glycoprotein (P-gp) was shown to bind ANXA2 and promote multidrug-resistant breast cancer invasion by regulating the phosphorylation of ANXA2, and further studies revealed that P-gp-mediated phosphorylation of ANXA2 is regulated by the receptor for activated C kinase 1 (RACK1)." (PMID 40234383, 2025). "Moreover, silencing of β-catenin inhibited breast cancer cell proliferation similarly to RACK1 knockdown, whereas β-catenin knockdown did not affect RACK1 expression, suggesting that RACK1 acts upstream of β-catenin." (PMID 37848434, 2023). "However, we did not identify any interaction between RACK1 and β-catenin or GSK3β in breast cancer cells." (PMID 37848434, 2023). "Thus, we evaluated the expression levels of OXER1 and RACK1 transcripts in estrogen-receptor-positive (ER+) and estrogen-receptor-negative (ER−) mammary tumors using the RNA-sequencing data available in the TCGA database." (PMID 33311444, 2020). "However, it is in NPC that there has been no report of the roles of RACK1, though RACK1 has been demonstrated to be a potential prognostic indicator in multiple cancers including breast cancer and pulmonary adenocarcinomas and so on." (PMID 27170279, 2016). "We then selected five breast cancer cell lines, including the triple-negative breast cancer (TNBC) cell lines MDA-MB-231 (MDA-231), BT549, and Hs578T, the luminal-type cell line T47D, and the HER2-positive cell line SK-BR-3, to investigate whether RACK1 regulates breast cancer cell proliferation." (PMID 37848434, 2023). "Thus, we reveal a novel mode of interaction between PSMD2, RACK1 and β-catenin, that may be a mechanism involved in regulating the activation of the WNT pathway, and targeting this pathway may be an effective way to treat breast cancer." (PMID 37848434, 2023). "Consistent with this hypothesis, we demonstrated that silencing of Rack1 expression significantly inhibited the proliferation and invasiveness in MDR breast cancer cells, which is consistent with previous reports that Rack1 was a promoter in breast cancer progression." (PMID 27754360, 2016). "The negative correlation of RACK1 and CCDC102B expression was not due to repressed transcription, as revealed by qRT–PCR analysis in breast cancer patients (n=177)." (PMID 35957886, 2022). "Both Rack1 and Src confer resistance to EPI in breast cancer cells by modulating P-gp activity without affecting its protein level." (PMID 31113938, 2019).
gastric cancer (33 papers, 2016 to 2025). A primary or metastatic malignant neoplasm involving the stomach. "Prior studies reported RACK1 negatively regulates NF-κB activity in gastric cancer cells, potentially explaining increased NF-κB activation in Usp17la−/− T cells." (PMID 41023441, 2025). "UBE2T is crucial in promoting gastric cancer progression by mediating the ubiquitination and degradation of RACK1, which leads to the over-activation of the Wnt/β-catenin signaling pathway—a key driver of tumor progression." (PMID 39791716, 2024). "In gastric cancer, cyclase-associated protein 2 (CAP2) bound to RACK1 and activated the SRC/FAK/ERK signaling pathway, leading to IL-4 and IL10 secretion, and M2 macrophage polarization." (PMID 38315284, 2024). "This possibility is partly supported by a recent study, which found that in gastric cancer cells, RACK1 is a short-lived protein that can be ubiquitinated and degraded by the ubiquitin-conjugating enzyme UBE2T." (PMID 37848434, 2023). "Although a previous study has shown that in gastric cancer cells, RACK1 promotes β-catenin degradation by interacting with GSK3β and stabilizing the β-catenin destruction complex." (PMID 37848434, 2023). "A previous report showed that RACK1 interacts with GSK3β and promotes β-catenin degradation in gastric cancer cells." (PMID 37848434, 2023). "A recent study revealed that UBE2T facilitated ubiquitin-dependent degradation of RACK1, a key scaffold protein stabilizing the β-catenin destruction complex in gastric cancer, leading to accumulation of β-Catenin and activation of the Wnt/pathway." (PMID 36357897, 2022). "We found that RACK1 expression level was similar between gastric cancer tissues and paired para-carcinoma tissues, which is consistent with GEPIA and Oncomine database." (PMID 33323973, 2021). "RACK1 depletions can also induce metastasis of gastric cancer (GC) by promoting the microRNA (miR)-302c/interleukin (IL)-8 axis." (PMID 32792866, 2020). "Except for colon and gastric cancer, Rack1 appears to play a tumor-promoting role in other carcinomas." (PMID 31113450, 2019). "Additionally, UBE2T promotes β-catenin nuclear translocation through the ubiquitin-mediated degradation of RACK1, facilitating gastric cancer progression." (PMID 39791716, 2024). "Interestingly, RACK1′s role changes in gastric cancer and pancreatic ductal adenocarcinoma, where it appears to act as a tumor suppressor." (PMID 39458945, 2024). "Nevertheless, RACK1 suppresses the proliferation and metastasis of gastric cancer cells and may also act as a tumor suppressor." (PMID 37848434, 2023). "Likewise, RACK1 accelerates the ubiquitination-mediated degradation of β-catenin in gastric cancer cells." (PMID 37848434, 2023). "Upregulation of UBE2T levels has been disclosed to enhance gastric cancer development through RACK1 ubiquitination, and a novel powerful UBE2T inhibitor has been identified to suppress gastric cancer progression by blocking RACK1 ubiquitination after aberrant Wnt/β-catenin signaling." (PMID 36910645, 2023). "MiR-302c/IL8 activates the RACK1-mediated receptor pathway to promote metastasis of gastric cancer, and low MiR-302c/IL8 expression is associated with invasion depth, tumor stage, and lymph node metastasis in gastric cancer." (PMID 32760226, 2020). "Intriguingly, RACK1 suppression promotes gastric cancer by modulating the expression of miRNAs78." (PMID 29396465, 2018). "For instance, upregulation of RACK1 expression accelerated tumorigenesis, progression, and metastasis in multiple tumors including hepatocellular carcinogenesis, oral squamous cell carcinoma, cervical cancer, and colon cancer, while it was reported to be a tumor suppressor gene in gastric cancer." (PMID 37591850, 2023).
gastric cancer (continued). "In order to determine how RACK1 protein level was downregulated in GC tissues, we tested the mRNA expression of RACK1 in 24 paired gastric cancer and para-carcinoma tissues." (PMID 33323973, 2021). "When Ser 124 of the receptor for activated C kinase 1, product of the RACK1 gene (formerly GNB2L1), was O-GlcNAcylated, the protein level of this receptor, which is a crucial mediator of EMT in gastric cancer metastasis, was dramatically reduced." (PMID 34356834, 2021). "In contrast, it has been reported that RACK1 is a negative regulator of NF-κB signalling in TNF-α-treated 293T cells, classical swine fever virus-infected PK-15 cells and Helicobacter pylori-infected gastric cancer cells." (PMID 37684678, 2023). "Notably, previous studies have shown that RACK1 is an inhibitor of β-catenin stability and WNT signaling in gastric cancer cells." (PMID 37848434, 2023). "Another group demonstrated that an ubiquitin-conjugating enzyme Ube2T directly interacts with RACK1 and induces RACK1 ubiquitination and degradation independent of the E3 ligase in gastric cancer cells." (PMID 35265209, 2022). "Aberrant expression of RACK1 has been reported in numerous cancers —particularly several squamous cell carcinomas such as esophageal squamous cell carcinoma (ESCC), oral squamous cell carcinoma (OSCC) and gastric cancer." (PMID 27170279, 2016). "Moreover, O-GlcNAcylation of RACK1 by OGT stabilizes RACK1, and results in a reduction of N-cadherin and upregulation of E-cadherin, indicating the induction of EMT and suppression of metastasis in chemoresistant gastric cancer." (PMID 33194731, 2020).